ZSWIM3 (zinc finger SWIM-type containing 3)
Synonyms: C20orf164; dJ337O18.7; PPP1R174
Tractability: PROTAC: ubiquitination databases record sites on it.
Gene: Protein-coding gene on chromosome 20 (45,857,614 to 45,879,131, forward strand). Ensembl gene ENSG00000132801.
Subcellular location (Human Protein Atlas): Vesicles; Cytosol; Nucleoli fibrillar center
Gene Ontology:
Molecular function: protein binding; zinc ion binding
Genetic constraint (gnomAD): Loss-of-function variants: 28 observed, 54.24 expected, observed/expected ratio (o/e) 0.52, 90% interval 0.38 to 0.71. The upper end of that interval is the gene's LOEUF score, 0.71, which puts it in group 2 of 6, group 1 being the genes least tolerant of losing a copy. Missense variants: 685 observed, 905.13 expected, observed/expected ratio (o/e) 0.76, 90% interval 0.71 to 0.81. Synonymous variants: 332 observed, 354.68 expected, observed/expected ratio (o/e) 0.94, 90% interval 0.86 to 1.02.
Homologues: Orthologues: chimpanzee ZSWIM3 (99% identical), macaque ZSWIM3 (96% identical), dog ZSWIM3 (87% identical), rabbit ZSWIM3 (86% identical), pig ZSWIM3 (85% identical), guinea pig ZSWIM3 (84% identical), mouse Zswim3 (80% identical), rat Zswim3 (77% identical), tropical clawed frog zswim3 (35% identical). Paralogues in human: ZSWIM1 (19% identical).
Diseases named in the same sentence as ZSWIM3 in open-access papers:
ZSWIM3 is named in the same sentence as 4 diseases in open-access papers, as found by Europe PMC text mining. Sharing a sentence is not in itself a finding about the gene and the disease. The quoted sentences say what the papers report.
breast carcinoma (1 paper, 2025). "A study showed that the overexpression of ZSWIM3 (zinc-finger SWIM domain-containing protein 3) in MCF-7 cells promotes breast cancer progression and metastasis by enhancing the levels of SREBF1, SREBF2, and the levels of lipids, the effect that was reversed when ZSWIM3 was knocked out." (PMID 40427160, 2025).
cancer (2 papers, 2022 to 2025). A tumor composed of atypical neoplastic, often pleomorphic cells that invade other tissues. "Four cancer-related hub genes (CRGs) were identified: Interferon Regulatory Factor 7 (IRF7), Formin Homology 2 Domain Containing 1 (FHOD1), Tumor Necrosis Factor (TNF), and Zinc Finger SWIM Domain Containing 3 (ZSWIM3)." (PMID 41262249, 2025).
ZSWIM3 also shares sentences with these, for which no sentence is quoted: gastric cancer (1 paper); uterine cancer (1).